S100A6 (S100 calcium binding protein A6)
Description:
May function as calcium sensor and modulator, contributing to cellular calcium signaling. May function by interacting with other proteins, such as TPR-containing proteins, and indirectly play a role in many physiological processes such as the reorganization of the actin cytoskeleton and in cell motility. Binds 2 calcium ions. Calcium binding is cooperative. (Microbial infection) Facilitates attachment and invasion of Toxoplasma gondii parasites.
Synonyms: PRA; CACY; 2A9; CABP; 5B10; S10A6
Tractability: Antibody: its Gene Ontology location is reachable by antibodies, with high confidence; UniProt places it where antibodies can reach, with medium confidence; the Human Protein Atlas places it where antibodies can reach. PROTAC: ubiquitination databases record sites on it; its protein half-life has been measured.
Gene: Protein-coding gene on chromosome 1 (153,534,591 to 153,536,549, reverse strand). Ensembl gene ENSG00000197956.
Subcellular location: Nucleus envelope; Cytoplasm; Cell membrane
Subcellular location (Human Protein Atlas): Cytosol; Plasma membrane
Gene Ontology:
Molecular function: calcium ion binding; calcium-dependent protein binding; protein binding; protein homodimerization activity; S100 protein binding; tropomyosin binding; identical protein binding; monoatomic ion transmembrane transporter activity; zinc ion binding
Biological process: axonogenesis; positive regulation of fibroblast proliferation; signal transduction; monoatomic ion transmembrane transport
Cellular component: cytoplasm; cytoplasmic side of plasma membrane; cytosol; extracellular exosome; extracellular matrix; extracellular region; nuclear envelope; nucleus; perinuclear region of cytoplasm; plasma membrane; ruffle
Genetic constraint (gnomAD): Loss-of-function variants: 5 observed, 5.44 expected, observed/expected ratio (o/e) 0.92, 90% interval 0.47 to 1.75. That is too few expected variants to judge how well the gene tolerates losing a copy. Missense variants: 114 observed, 110.87 expected, observed/expected ratio (o/e) 1.03, 90% interval 0.88 to 1.2. Synonymous variants: 48 observed, 48.27 expected, observed/expected ratio (o/e) 0.99, 90% interval 0.79 to 1.26.
Homologues: Orthologues: chimpanzee S100A6 (100% identical), macaque S100A6 (100% identical), mouse S100a6 (96% identical), rat S100a6 (94% identical), pig S100A6 (89% identical), zebrafish s100s (44% identical), zebrafish s100t (44% identical). Paralogues in human: S100A4 (52% identical), S100A5 (50% identical), S100A2 (49% identical), S100A3 (46% identical), S100A1 (44% identical), S100B (40% identical), S100Z (39% identical), S100A12 (36% identical), S100P (34% identical), S100A13 (33% identical), S100A11 (32% identical), S100A9 (31% identical), and 9 more.
Diseases named in the same sentence as S100A6 in open-access papers:
S100A6 is named in the same sentence as 188 diseases in open-access papers, as found by Europe PMC text mining. Sharing a sentence is not in itself a finding about the gene and the disease. The quoted sentences say what the papers report.
breast cancer (65 papers, 1998 to 2024). A primary or metastatic malignant neoplasm involving the breast. "Our results indicated that high mRNA expression of S100A8, S100A9, S100A11 and S100P were found to be significantly correlated to worse outcome, while S100A1 and S100A6 were associated with better prognosis in all breast cancer patients." (PMID 28051137, 2017). "In vitro, S100A6 inhibited the clonogenicity of breast cancer cells and enhanced their sensitivity to paclitaxel-induced cytotoxicity, apoptosis, and G2/M phase arrest." (PMID 37217945, 2023). "S100A6 (calcium-binding protein A6) is upregulated in breast cancer through mesenchymal stem cell-secreted exosomes to promote chemotherapy resistance." (PMID 36980828, 2023). "This study examined the expression of S100A6 in different breast cancer cell lines and focused on the role of S100A6 in the progression and chemotherapy of breast cancer." (PMID 37217945, 2023). "In both breast cancer cells and xenograft model, S100A6 suppressed the tumor growth and enhanced its sensitivity to paclitaxel, which were dependent on MDM2 inhibition." (PMID 37217945, 2023). "And, high expression of S100A6 was determined to be an independent factor in predicting pCR, suggesting that S100A6 was a predictive biomarker for efficacy of neoadjuvant chemotherapy in breast cancer patients." (PMID 37217945, 2023). "The role of S100A6 signaling in breast cancer has previously been reported; it promotes the function of cacy/SIP, which is related to tumor invasion and metastasis by increasing β-catenin levels." (PMID 36613714, 2022). "To test this, we analyzed protein expression of S100A6 and S100B via IHC of TMAs containing patient sample biopsies from different stages of breast cancer totaling 160 cores." (PMID 32211331, 2020). "Survival analysis of patients with different expression of S100A6 revealed correlation of high S100A6 expression with worse outcome in survival of breast cancer patients." (PMID 32211331, 2020). "In saliva, three proteins of the S100A family, namely S100A2, S100A4, and S100A6, were among the most upregulated proteins in bitches with mammary tumors when compared to healthy controls." (PMID 32344524, 2020). "The TMA co-registration analysis showed correlation of S100A6 with LAMP2b expression the most in early breast cancer stage, ductal carcinoma in situ, DCIS." (PMID 32211331, 2020). "We then continued our analysis with S100A6 by measuring the positivity of each core in different stages of breast cancer." (PMID 32211331, 2020). "In contrast, a recent study suggests a relation between S100A6 expression and better prognosis in breast cancer." (PMID 32344524, 2020). "According to our results, increased mRNA expression of S100A6 was correlated to better prognosis, especially in luminal A type breast cancer." (PMID 28051137, 2017). "S100 genes have a role in breast cancer progression, and it has been reported a decrease in S100a6 concomitantly with a reduction in oxidative stress." (PMID 26091908, 2016). "Decreased S100A6 expression in breast cancer has been linked to a worse prognosis regardless of subtype." (PMID 38630893, 2024). "Upon investigating the mammary tumor tissue from docetaxel-treated mice, we found an increase in protumor immune infiltrates including M2 macrophages, MDSCs, Tregs, γδT cells, and an enriched gene signature comprising Vim, Spp1, S100a6, Ccl2, and Lgals1 genes." (PMID 37699010, 2023). "Furthermore, the S100A6-mediated MDM2 degradation suppressed the growth of breast cancer and enhanced its sensitivity to paclitaxel both in vitro and in vivo." (PMID 37217945, 2023). "Next, whether S100A6 could suppress the growth of breast cancer cells and enhance their sensitivity to chemotherapy was investigated." (PMID 37217945, 2023). "Moreover, the S100A6-mediated MDM2 degradation suppressed the growth of breast cancer and enhanced sensitivity to paclitaxel both in vitro and in vivo." (PMID 37217945, 2023).
breast cancer (continued). "Previous research reported that S100A6 impaired lymphatic endothelial cells tight junction and increased the transendothelial migration of neutrophils in breast cancer, indicating that S100α6 might be a potential mLECs damage biomarker after SAH." (PMID 37211686, 2023). "Mechanistically, lymphatic endothelium–neutrophil interactions, neutrophil N2-type phenotypic reprogramming and S100A6 upregulation in various lung host cells, further support inflammation-associated events which contribute to the formation of a lung PMN in mice with breast cancer." (PMID 36612175, 2022). "Our findings suggest that S100A6 released from proliferative lymphatic ECs attracts neutrophils and might trigger host pulmonary remodeling before lung metastasis of breast cancer." (PMID 36612175, 2022). "Similarly, MSCs-secreted exosomes have been found to promote doxorubicin (DOX) resistance by inducing S100A6 expression in MDA-MB-231 breast cancer cells." (PMID 36100944, 2022). "In contrast, S100A6 levels are decreased in human breast cancer cell lines." (PMID 36613714, 2022). "Upregulation of miR-21-5p has been detected in both MSCs and MSC-secreted exosomes after exposure to DOX, and MSCs-secreted exosomes could potentiate DOX resistance via miR-21-5p-mediated induction of S100A6 expression in breast cancer in vitro and in vivo." (PMID 36100944, 2022). "Only a few studies have been performed to investigate the signalling of S100A6 in breast cancer." (PMID 32722137, 2020). "Therefore, elevating the expression level of S100A6 in breast cancer cells can not only promote the degradation of the oncoprotein MDM2 and inactivate some cancer progression pathways, but also lower the occurrence of chemoresistance, achieving better therapeutic effects." (PMID 37217945, 2023). "By disrupting the MDM2–HAUSP–DAXX-HAUSP-DAXX complex, S100A6 induces MDM2 self-ubiquitination and its degradation, which suppresses the growth of breast cancer and enhances its sensitivity to chemotherapy." (PMID 37217945, 2023). "Correlation analysis of S100A6 and LAMP2b as marker of acidosis in each patient from Moffitt TMA approved the acid related role of S100A6 in breast cancer patients." (PMID 32211331, 2020). "This suggests a role for S100 genes, specifically S100A6, in the migratory phenotype observed in HER2-overexpressing breast cancer cells with acquired trastuzumab resistance." (PMID 30736768, 2019). "Since S100A6 consistently demonstrated higher levels in all three lines we tested, we sought to determine the role of S100A6 in HER2-overexpressing breast cancer cells and in EGF/EGFR cell signaling through siRNA knockdown experiments." (PMID 30736768, 2019). "S100A5, S100A6, S100A8 and S100A9 were correlated with prognosis in luminal A type breast cancer patients." (PMID 28051137, 2017). "However, the prognostic role of S100A6 in breast cancer is unknown." (PMID 28051137, 2017). "Amplification of this region had not previously been associated with sarcoma development, but occasional amplification of CACY/S100A6 and MUC1 in 1q21 had been reported for melanoma and breast carcinoma respectively." (PMID 9716033, 1998). "The co-immunoprecipitation first demonstrated that S100A6 and MDM2 could interact with each other in breast cancer cells." (PMID 37217945, 2023). "However, S100A6 induces the activity of calcyclin-binding protein/Siah-1-interacting protein (Cacy/SIP), which is involved in tumour invasion and metastasis in breast cancer most likely by increasing β-catenin levels." (PMID 32722137, 2020). "Furthermore, our data confirmed that S100A6 and S100A2 were significantly increased in trastuzumab resistant breast cancer cells, SKBR3/100–8." (PMID 30736768, 2019). "In addition, clonogenic assay, WST-1 assay, and flow cytometry of apoptosis and the cell cycle were performed and a xenograft model was established to evaluate the effects of the S100A6/MDM2 interaction on growth and paclitaxel-induced chemosensitivity of breast cancer." (PMID 37217945, 2023).
breast cancer (continued). "S100A6 could be potential target for treating HER2 and EGFR positive breast cancer." (PMID 30736768, 2019). "However, the expression of S100A6 in breast cancer is not yet conclusive." (PMID 37217945, 2023).
pancreatic cancer (29 papers, 2009 to 2024). "It has been reported that S100A6 is over-expressed and associated with disease development and malignant progression in gastric cancer, pancreatic cancer, and colon cancer but under-expressed in prostate cancer and oral cancer." (PMID 37217945, 2023). "Overexpression of S100A6 has been associated with poor prognosis in lung, gastric and pancreatic cancer." (PMID 21305022, 2011). "Analysis of primary pancreatic cancer specimens (n=55) revealed a strong association between high levels of cytoplasmic S100A6 and the presence of annexin 2 in the plasma membrane of cancer cells (P=0.009)." (PMID 19724273, 2009). "Depletion of S100A6 was accompanied by diminished levels of membrane annexin 2 and caused a pronounced reduction in the motility of pancreatic cancer cells." (PMID 19724273, 2009). "The most striking phenotype of S100A6 depletion from pancreatic cancer cells in our study was the dramatic loss of cell motility, observed in both Boyden chamber and wound healing assays." (PMID 19724273, 2009). "Moreover, some studies have shown that S100A6 mRNA quantification is a promising diagnostic method and therapeutic target for pancreatic cancer." (PMID 37670392, 2023). "Measuring the content of S100A6 in pancreatic juice may help identify early pancreatic cancer or high-risk individuals who may develop pancreatic cancer." (PMID 37670392, 2023). "Furthermore, high nuclear localization of S100A6, a low molecular weight calcium binding protein that belongs to S100 family of proteins, is significantly associated with poor survival in pancreatic cancer patients." (PMID 25275504, 2014). "In pancreatic cancer, the expression of S100A6 appears to correlate with aggressive disease in that high levels of tumour S100A6 are associated with poorer outcome, whereas pancreatic cancer cells depleted of S100A6 are less invasive." (PMID 19724273, 2009). "Given the association of S100A6 with annexin 2 and the role of the latter in actin binding and motility, we questioned whether S100A6 may therefore contribute to the motility of pancreatic cancer cells." (PMID 19724273, 2009). "High levels of S100A6 have been associated with poor outcome in pancreatic cancer patients." (PMID 19724273, 2009). "This mutation in the S100A6 gene enhancer could have functional consequences in pancreatic cancer." (PMID 35449156, 2022). "As expected, many differential SE-associated genes in PSN1 were the key genes of pancreatic cancer, such as S100A4, S100A6, S100A2, NTSR1 and CDK5." (PMID 36318264, 2023). "In our study, the transcripts of both S100A4 and S100A6 were found at a high level in the HPNE cells when compared to the pancreatic cancer cells." (PMID 37627239, 2023). "Current data show that S100A6 levels increase hierarchically during the occurrence of pancreatic cancer." (PMID 37670392, 2023). "S100A6 is also an up-regulated S100As in pancreatic cancer confirmed by bioinformatics and in vitro experiments." (PMID 34530774, 2021). "Overexpression of S100A6 in pancreatic carcinoma was also found in Pei’s dataset (fold change = 9.15) and Segara’s dataset (fold change = 4.76)." (PMID 34804125, 2021). "S100A6 was found to be overexpressed, especially in the early phase of carcinogenesis, and high nuclear S100A6 levels predict poor survival of pancreatic cancer patients." (PMID 32722137, 2020). "Another study identified S100A6 as a pancreatic cancer biomarker in cell lines, using laser capture microdissection, two-dimensional gel electrophoresis (2-DE), MS, and immunohistochemistry." (PMID 30771135, 2019). "Increased S100A6 level has been observed in many tumors, such as melanoma, colorectal carcinoma, and pancreatic cancer." (PMID 28423550, 2017). "S100A4 has been reported to enhance pancreatic cancer cell invasion via the regulation of E-cadherin expression, and overexpression of S100A6 has been reported to result in the downregulation of E-cadherin." (PMID 25780452, 2015).
pancreatic cancer (continued). "It has also been reported that a strong association is between the presence of annexin II in the plasma membrane and high levels of cytoplasmic S100A6 of pancreatic cancer cells." (PMID 22681645, 2012). "Confirmed genes included genes already reported in the literature and proposed as biomarkers of pancreatic cancer such as S100A6, TIMP1, NF-κB, VCL and S100P." (PMID 22078386, 2011). "This set included genes already reported in the literature as differentially expressed in pancreatic cancer and that have been investigated as biomarkers for pancreatic cancer (i.e. S100A6, S100P, TIMP1 and NF-κB)." (PMID 22078386, 2011). "In summary, our study has provided insight into candidate S100A6-binding partners in pancreatic cancer and has shown a positive relationship between the cellular levels of S100A6 and the localisation of annexin 2 to the cell membrane." (PMID 19724273, 2009). "Our study identified the known S100A6-binding proteins, tropomyosin β, annexin 11 and annexin 2 as well as novel binding protein lamin B1, as candidate S100A6 interactors in pancreatic cancer cells." (PMID 19724273, 2009). "Of these, annexin 2 was considered particularly interesting, as, like S100A6, it is expressed early in the development of pancreatic cancer and overexpression occurs with high frequency in invasive cancer." (PMID 19724273, 2009). "Reciprocal immunoprecipitation confirmed the interaction between annexin 2 and S100A6 and the proteins colocalised, particularly in the plasma membrane of cultured pancreatic cancer cells and primary pancreatic tumour tissue." (PMID 19724273, 2009). "We described earlier the expression profile of S100A6 in tumours from 60 pancreatic cancer patients." (PMID 19724273, 2009). "Several studies have identified overexpression of S100A6 in pancreatic cancer, in PanIN lesions and in intraductal papillary mucinous neoplasms." (PMID 19724273, 2009). "Colocalisation of S100A6 and Annexin 2 was also observed in the plasma membranes of paraffin-embedded sections from primary pancreatic tumour material." (PMID 19724273, 2009). "Therefore, this study involves the identification of various overexpressed protein members of the S100 protein family, including S100-A4, S100-A6, S100-A8, S100-A9, and S100-A11, to develop a successful multiepitope-based vaccine against pancreatic cancer." (PMID 38976715, 2024). "This suggested that, although S100A6 was expressed in early pancreatic cancer, nuclear S100A6 could serve as an independent prognostic factor." (PMID 37304241, 2023). "Moreover, the inhibition of S100A6 expression reduced the proliferation and invasiveness of pancreatic cancer cells." (PMID 36318264, 2023). "However, in the pancreatic tumor array, correlations were observed between S100A6 and S100A11 (R = 0.49) and S100A14 (R = 0.45)." (PMID 37627239, 2023). "A study reported that S100A6 is elevated during the carcinogenesis of pancreatic cancer." (PMID 36072587, 2022). "Further research is needed to explain the role of S100A6 in the development of pancreatic cancer." (PMID 34530774, 2021). "S100A6 has been suggested to promote EMT through β-Catenin in a pancreatic cancer cell line." (PMID 30736768, 2019). "Indeed, previous studies proposed S100A6 as potential therapeutic target in pancreatic cancer and gastric cancer." (PMID 28206967, 2017). "S100A6 may therefore represent a novel potential therapeutic target for the treatment of pancreatic cancer." (PMID 25799022, 2015). "Furthermore, increased cell surface expression of ANX2 and its interacting partner S100A6 was noticed in patients suffering from pancreatic cancer." (PMID 25407528, 2014). "A functional role for S100A6 in pancreatic cancer has, nevertheless, remained elusive." (PMID 19724273, 2009). "Finally, our findings provide new insight into S100A6 function, namely that it promotes pancreatic cancer cell motility." (PMID 19724273, 2009).